LTF (lactotransferrin)
Diseases named in the same sentence as LTF in open-access papers (continued):
Sharing a sentence is not in itself a finding about the gene and the disease.
pneumonia (3 papers, 2008 to 2018). An acute, acute and chronic, or chronic inflammation focally or diffusely affecting the lung parenchyma, caused by an infection in one or both of the lungs (by bacteria, viruses, fungi, or mycoplasma.). "Of interest, the RNA abundance of five genes were altered by pneumonia in both the mouse and human gene sets: lactotransferrin (LTF), cathelicidin antimicrobial peptide (CAMP), phospholipid scramblase 1 (PLSCR1), inhibin beta A (INHBA), and hydroxyprostaglandin dehydrogenase 15-(NAD) (HPGD)." (PMID 18270561, 2008). "The top 50 over-abundant transcripts in pneumonia were dominated by antimicrobial neutrophil-related genes e.g ELANE, DEFA1B, MMP8, CAMP, DEFA3, DEFA4, MPO, LTF." (PMID 23940611, 2013).
systemic lupus erythematosus (3 papers, 2022 to 2025). An autoimmune multi-organ disease typically associated with vasculopathy and autoantibody production. "We identified two transcription factors (STAT1 and LTF) that were positively correlated with T-cell subset infiltration in the lupus tubulointerstitium, and three transcription factors (IRF8, RORC and IKZF2) that were positively associated with T-cell subset infiltration in the glomeruli." (PMID 36829595, 2023).
thyroid cancer (3 papers, 2021 to 2024). "In addition, LTF gene expression is decreased in thyroid cancer patients." (PMID 34522174, 2021).
allergic asthma (2 papers, 2019 to 2020). A asthma with a basis in a pathological type I hypersensitivity reaction. "Thus, being a hub gene also as elucidated in our study, LTF can be suggested as a putative tool to track the progression or the drug efficacy in allergic asthma patients." (PMID 32770056, 2020).
allergies (2 papers, 2016 to 2021). "The lack of breast milk feeding during the first six months, an important source of secretory IgA, lysozyme and lactotransferrin, increases the risk of infections including respiratory infections as well as the risk of allergy." (PMID 27642394, 2016).
amyloid (2 papers, 2022). "While higher PRTN3 may be protective, an interaction between immune genes, the amyloid-related LTF, and the tau-related ADAMTS2 could provide insights into how amyloid accelerates tau pathology." (PMID 35557837, 2022).
anaemia (2 papers, 2021 to 2024). "The results of numerous studies indicate that diet supplementation with lactoferrin (LTF), an iron-binding protein, may be advantageous in prophylaxis and treatment of iron deficiency anemia." (PMID 34440102, 2021). "On the other hand, the lack of iron ions in the examined patients infected with Helicobacter pylori and accompanied by anaemia could have resulted in insufficient synthesis of lactotransferrin and its low concentrations noted in our study." (PMID 39684489, 2024).
dementia (2 papers, 2017 to 2025). Loss of intellectual abilities interfering with an individual's social and occupational functions. "However, it requires improved testing systems that could differentiate between LTF isoforms, their fragments, and their iron-binding states for disentangling the systemic and brain-specific roles of LTF in the pathophysiology of AD and related dementias." (PMID 41256130, 2025). "Targeted re-sequencing of the six candidate genes (LTF, MME, UBE4A SORL1, FAM221A and KDM2B) was performed in 35 EOAD cases with a family history of dementia." (PMID 28595629, 2017).
diabetic retinopathy (2 papers, 2021 to 2025). "Regarding the inflammatory process, in tears, lactotransferrin, lipocalin 1 (LCN-1), lysozyme C, lipophilin A, lacritin, and immunoglobulin lambda chain levels increased in patients with diabetic retinopathy." (PMID 34575451, 2021).
Hypertension (2 papers, 2019 to 2020). The presence of chronic increased pressure in the systemic arterial system. "In addition, for an additive genetic model, but not for dominant genetic model, researchers observed a trend for a significant association of LTF rs1126478 with hypertension." (PMID 32957486, 2020). "CYP3A4, APOA2, PPARG, ALOX, and CYP4F2, proteins related to lipid homeostasis affect the occurrence of hypertension, and PTGER2, ALOX5, LTF, ITGB, and GATA3 relate to the inflammatory and immune response in glomeruli." (PMID 30809144, 2019).
keratoconus (2 papers, 2016 to 2022). A degenerative, structural disorder of the eye, characterized by a cone-shaped protrusion of the cornea. "Keratoconus (KC) is a corneal disorder whose etiology shares a close relationship with Lactoferrin (LTF) dysregulation and Toll-like Receptors 2 (TLR2) overexpression." (PMID 36293206, 2022).
leukemia (2 papers, 2018 to 2019). A malignant (clonal) hematologic disorder, involving hematopoietic stem cells and characterized by the presence of primitive or atypical myeloid or lymphoid cells in the bone marrow and the blood. "For instance, ORM1 and ORM2 are already shown to be involved in AML, LTF is a high-profile gene whose role in AML needs further investigation, and S100A12 is shown to be involved in similar subtypes of leukemia, such as ALL, and is suggested to be involved in AML as well." (PMID 29589558, 2018).
malaria (2 papers, 2019 to 2025). Malaria is a serious and sometimes fatal disease caused by a parasite that commonly infects a certain type of mosquito which feeds on humans. "In our analyses, IL1R2, LCN2, LTF, and MMP8 were associated with all SM subgroup comparisons to uncomplicated malaria." (PMID 40383794, 2025). "In light of the reported association with septic shock, our associations of elevated IL1R2, LCN2, LTF, MMP8, and OLMF4 in SM subtypes compared to uncomplicated controls may reflect a general signature of the inflammatory reaction to severe infection and may not represent a malaria-specific pathway." (PMID 40383794, 2025).
non-small cell lung carcinoma (2 papers, 2018 to 2026). A group of at least three distinct histological types of lung cancer, including non-small cell squamous cell carcinoma, adenocarcinoma, and large cell carcinoma. "The overexpression of LTF significantly inhibited ferroptosis in non-small cell lung cancer cells." (PMID 41777684, 2026).
papillary thyroid cancer (2 papers, 2020 to 2022). "For patients with papillary thyroid carcinoma, macrophages, mast cells, natural killer (NK) cells, Tfh cells, activated dendritic cells (aDCs), B cells, Tregs, CD8 + T cells and DCs were associated with LTF expression, which indicated that LTF plays an important role in the tumor microenvironment." (PMID 35654816, 2022).
active tuberculosis (1 paper, 2024). "LTF and LCN2 were also induced during a septic shock, and MPO, LCN2, and LTF were used to distinguish between latent and active tuberculosis." (PMID 39409176, 2024).
acute leukemia (1 paper, 2022). A clonal (malignant) hematopoietic disorder with an acute onset, affecting the bone marrow and the peripheral blood. "Moreover, the lower antimicrobial activity of neutrophils may be specific for acute leukemia and the acute phase of chronic leukemia as indicated by LTF immunoreactivity." (PMID 36230605, 2022).
adenomatous colon polyp (1 paper, 2022). A polypoid adenoma that arises from and protrudes into the lumen of the colon. "Furthermore, lactotransferrin was found as gradually increased in non-adenomatous colon polyp, non-metastatic CC, and metastatic CC tissues when compared to the normal colon." (PMID 35495697, 2022).
autoimmune disease (1 paper, 2014). A disorder resulting from loss of function or tissue destruction of an organ or multiple organs, arising from humoral or cellular immune responses of the individual to their own tissue constituents. "Interestingly, the three genes (LTF, CAMP, and DEFA4, encoding lactoferrin, cathelicidin, and α-defensin 4) were closely related to immune function and autoimmune diseases." (PMID 24741625, 2014).
bacterial pneumonia (1 paper, 2024). Acute infection of the lung parenchyma caused by bacteria (e.g., Streptococcus pneumoniae, Haemophilus influenzae, Chlamydia pneumoniae, Mycoplasma pneumoniae, and Legionella pneumophila). "For example, LTF, MPO, LCN2, and S100A9 are markers of neutrophil degranulation previously associated with bacterial pneumonia." (PMID 39409176, 2024).
brain edema (1 paper, 2017). Increased intracellular or extracellular fluid in brain tissue. "However, we have also demonstrated here that LTF (a protein whose main systemic source is circulating PMNs) is upregulated in PMNs in response to IL-27 and that LTF, when used therapeutically, protects from ICH-induced brain edema and neural tissue damage." (PMID 28928459, 2017).
brain tumors (1 paper, 2023). "LTF expression is reduced in GBM compared with lower-grade brain tumors and can inhibit GBM cell proliferation." (PMID 37252795, 2023).
breast tumors (1 paper, 2020). "Previous research has shown that the correlation between the expression of LTF in breast tumors and the life expectancy of patients is important." (PMID 32244557, 2020).
cervical cancer (1 paper, 2023). A primary or metastatic malignant neoplasm involving the cervix. "Previous studies have shown that in cervical cancer, high expression of LTF can activate the NF-κB signaling pathway and further lead to the activation of downstream target genes." (PMID 37168259, 2023).
coronary artery stenosis (1 paper, 2020). "Previously, LTF gene polymorphisms were reported to be associated with lactoferrin levels and coronary artery stenosis." (PMID 32957486, 2020).
cutaneous melanoma (1 paper, 2020). A primary melanoma arising from atypical melanocytes in the skin. "In addition, compared with the normal control, the expression of IGHV1-18, CXCL11 and HLA-DQB1 were higher in the patients with cutaneous melanoma, while the expression of LTF was lower." (PMID 33585219, 2020). "We found that the expression of CXCL11 (P = 0.1), LTF (P = 0.28), and HLA-DQB1 (P = 0.67) had no significant relation to the subtypes of cutaneous melanoma through TISIDB database." (PMID 33585219, 2020).
disc degeneration (1 paper, 2024). "Moreover, injecting recombinant human Lactotransferrin (rehLTF) also alleviated disc degeneration caused by the acupuncture model." (PMID 39392081, 2024). "Subsequent downregulation of LTF led to increased phosphorylation of JAK2 and STAT3, culminating in enhanced CEP calcification, senescence and ECM degradation, thereby contributing to disc degeneration." (PMID 39392081, 2024).
endothelial dysfunction (1 paper, 2026). In vascular diseases, endothelial dysfunction is a systemic pathological state of the endothelium (the inner lining of blood vessels) and can be broadly defined as an imbalance between vasodilating and vasoconstricting substances produced by (or acting on) the endothelium. "In vitro experiments revealed that blood neutrophils had significantly increased expression of LTF and VEGFA following LPS-stimulation and heme induces endothelial dysfunction." (PMID 41568397, 2026).
gastroenteritis (1 paper, 2020). An inflammatory disorder that affects the upper and lower gastrointestinal tract. "The gene lactotransferrin was linked to Aeromonas, which has been associated with gastroenteritis and skin infections and has been previously reported to bind lactoferrin." (PMID 32571363, 2020).
gingivitis (1 paper, 2025). A disorder involving inflammation of the gums; may affect surrounding and supporting structures of the teeth. "Recent findings align with our results showing a 1.6-fold increase in Lactotransferrin in individuals with gingivitis, reflecting its role in countering bacterial biofilm formation." (PMID 40366920, 2025).
gout (1 paper, 2022). A condition characterized by painful swelling of the joints, which is caused by deposition of urate crystals. "With the criteria of unique peptides ≥ 2, 25 proteins were found highly expressed in gout uniquely, lysozyme C, alpha-1-acid glycoprotein 1, lactotransferrin, protein S100-A9, and myeloperoxidase included." (PMID 35359923, 2022).
helminthic infections (1 paper, 2022). "Lactotransferrin is a glycoprotein involved in the innate immune response to viral, bacterial and helminthic infections." (PMID 35271623, 2022).
hemorrhagic stroke (1 paper, 2022). A stroke caused by a bleed on the brain. "Although LTF is believed to mediate neuronal ferroptosis in hemorrhagic stroke, it has rarely been reported in IS." (PMID 36685826, 2022).
Immunodeficiency (1 paper, 2021). Failure of the immune system to protect the body adequately from infection, due to the absence or insufficiency of some component process or substance. "As the core gene of the PRAD immune microenvironment, the low expression of LTF in PRAD promotes the occurrence of immunodeficiency, PRAD, and the enrichment of the Janus kinase (JAK)/STAT3 signal pathway." (PMID 34868909, 2021).
iron disorders (1 paper, 2023). "LTF is emerging as a potent regulator of iron and inflammatory homeostasis, which is the sole glycoprotein able to contemporarily act against microbial multiplication, biofilm formation, iron disorders, oxidative stress, and viral and parasitic infections as well as inflammation." (PMID 36820206, 2023).
liver cancer (1 paper, 2008). An epithelial or non-epithelial malignant neoplasm that arises from the liver. "It has been reported that bovine lactotransferrin significantly inhibits colon, esophagus, lung, bladder and liver cancers in rats." (PMID 19055846, 2008).
lung squamous cell carcinoma (1 paper, 2023). "Neat1 has been shown to sponge miR-214-5p to reduce LTF expression, thus promoting autophagy in lung squamous cell carcinoma cells." (PMID 37716986, 2023).
neurofibroma (1 paper, 2020). An intraneural or extraneural neoplasm arising from nerve tissues and neural sheaths. "Conversely, the transferrin family member LTF was relatively hypermethylated in orbitofacial NF compared to the non-orbital neurofibromas." (PMID 32366326, 2020).
oral disease (1 paper, 2025). "Genetic variation in the LTF gene has been linked to several systemic and oral diseases, including Parkinson's disease, breast cancer, leukemia, and aggressive periodontitis." (PMID 40255521, 2025).
Peri-Implantitis (1 paper, 2025). An inflammatory process with loss of supporting bone in the tissues surrounding functioning DENTAL IMPLANTS. "The aim was to evaluate the association between single-nucleotide polymorphisms (SNPs) in genes involved in inflammation and bone metabolism (BMP-4, BRINP3, CD14, FGF-3, FGF-10, GBP-1, IL-1α, IL-1β, IL-10, LTF, OPG, and RANKL) and peri-implantitis." (PMID 41373620, 2025).
primary immunodeficiency (1 paper, 2021). "We found that the high expression of LTF in tumors can promote mismatch repair, nucleotide excision repair, and other pathways, while the low expression of LTF is related to primary immunodeficiency, JAK/STAT signaling pathway, cancer pathway, PRAD, and other pathways’ enrichment." (PMID 34868909, 2021).
prostate tumor (1 paper, 2020). "LTF downregulation in prostate tumor cells is remarkably associated with prostate-specific antigen recurrence after radical prostatectomy." (PMID 32244557, 2020).
psoriasis (1 paper, 2024). An autoimmune condition characterized by red, well-delineated plaques with silvery scales that are usually on the extensor surfaces and scalp. "Other psoriasis-specific enriched pathways included lipid metabolism (e.g. ACOT4, S1PR3), keratinization (e.g. LCE5A, KRT5/7/16), neutrophil degranulation, and antimicrobial peptides (e.g. LTF, DEFB4A, S100A7-9)." (PMID 38433843, 2024).
pterygium (1 paper, 2020). A wedge-shaped fibrovascular lesion arising from the bulbar conjunctiva and extending to the cornea. "From the results of RNA-Seq, LCN1, LTF, SCGB2A1, HBA1 (hemoglobin subunit alpha 1) and HBA2 (hemoglobin subunit alpha 2) ranked as the top five DEGs in the comparison between pterygium and normal tissues." (PMID 32411530, 2020). "The mRNA expressions of SCGB2A1, LTF and LCN1 were significantly decreased in pterygium tissues compared with normal control tissues, while the mRNA levels of HBA1 and HBA2 were higher in the pterygium tissues than in the control tissues." (PMID 32411530, 2020).
SARS-CoV infection (1 paper, 2021). "LF gene (LTF, lactotransferrin) expression has been previously shown to be highly up-regulated in response to the SARS-CoV infection." (PMID 33954061, 2021).
Shock (1 paper, 2021). The state in which profound and widespread reduction of effective tissue perfusion leads first to reversible, and then if prolonged, to irreversible cellular injury. "OLFM4 and LTF were subpopulations of neutrophils in septic shock." (PMID 34692829, 2021).
soft tissue sarcoma (1 paper, 2025). A malignant neoplasm arising from muscle tissue, adipose tissue, blood vessels, fibrous tissue, or other supportive tissues excluding the bones. "LTF is an iron binding transport protein and its engineered overexpression in soft tissue sarcomas was shown to be associated with metastasis." (PMID 40988744, 2025).
T-cell lymphomas (1 paper, 2013). "However, frequently rearranged in advanced T-cell lymphomas (FRAT1) and LTF exhibited the same pattern of expression by RT-qPCR and microarray analyses." (PMID 23324411, 2013).